AIFM2 (AIF family member 2, ferroptosis suppressor)
Description:
A NAD(P)H-dependent oxidoreductase that acts as a key inhibitor of ferroptosis. At the plasma membrane, catalyzes reduction of coenzyme Q/ubiquinone-10 to ubiquinol-10, a lipophilic radical-trapping antioxidant that prevents lipid oxidative damage and consequently ferroptosis. Acts in parallel to GPX4 to suppress phospholipid peroxidation and ferroptosis. This anti-ferroptotic function is independent of cellular glutathione levels. Also acts as a potent radical-trapping antioxidant by mediating warfarin-resistant vitamin K reduction in the canonical vitamin K cycle: catalyzes NAD(P)H-dependent reduction of vitamin K (phylloquinone, menaquinone-4 and menadione) to hydroquinone forms. Hydroquinones act as potent radical-trapping antioxidants inhibitor of phospholipid peroxidation and ferroptosis. May play a role in mitochondrial stress signaling. Upon oxidative stress, associates with the lipid peroxidation end product 4-hydroxy-2-nonenal (HNE) forming a lipid adduct devoid of oxidoreductase activity, which then translocates from mitochondria into the nucleus triggering DNA damage and cell death. Capable of DNA binding in a non-sequence specific way.
Synonyms: FSP1; AMID; PRG3; FLJ14497
Tractability: Small molecule: a structure with a bound ligand is known. Antibody: UniProt places it where antibodies can reach, with high confidence; its Gene Ontology location is reachable by antibodies, with high confidence; UniProt predicts a signal peptide or a membrane-spanning region. PROTAC: UniProt records ubiquitination sites on it; ubiquitination databases record sites on it; its protein half-life has been measured.
Target class: Enzyme; Oxidoreductase
Gene: Protein-coding gene on chromosome 10 (70,097,053 to 70,133,269, reverse strand). Ensembl gene ENSG00000042286.
Subcellular location: Lipid droplet; Cell membrane; Cytoplasm; Mitochondrion membrane; Nucleus
Subcellular location (Human Protein Atlas): Vesicles; Cytosol; Plasma membrane
Gene Ontology:
Molecular function: DNA binding; electron-transferring-flavoprotein dehydrogenase activity; flavin adenine dinucleotide binding; oxidoreductase activity, acting on NAD(P)H, quinone or similar compound as acceptor; protein binding; NADH dehydrogenase (quinone) (non-electrogenic) activity; NADPH dehydrogenase (quinone) activity; oxidoreductase activity
Biological process: apoptotic mitochondrial changes; cellular detoxification; negative regulation of ferroptosis; positive regulation of apoptotic process; ubiquinone metabolic process; vitamin K metabolic process; regulation of cellular response to oxidative stress; respiratory electron transport chain
Cellular component: cytoplasm; cytosol; extracellular region; lipid droplet; mitochondrial membrane; mitochondrial outer membrane; mitochondrion; nucleus; plasma membrane
Genetic constraint (gnomAD): Loss-of-function variants: 36 observed, 33.86 expected, observed/expected ratio (o/e) 1.06, 90% interval 0.81 to 1.4. The upper end of that interval is the gene's LOEUF score, 1.4, which puts it in group 5 of 6, group 1 being the genes least tolerant of losing a copy. Missense variants: 471 observed, 503.59 expected, observed/expected ratio (o/e) 0.94, 90% interval 0.87 to 1.01. Synonymous variants: 185 observed, 210.63 expected, observed/expected ratio (o/e) 0.88, 90% interval 0.78 to 0.99.
Homologues: Orthologues: chimpanzee AIFM2 (99% identical), macaque AIFM2 (99% identical), rat Aifm2 (91% identical), mouse Aifm2 (90% identical), guinea pig AIFM2 (90% identical), rabbit AIFM2 (89% identical), pig AIFM2 (87% identical), dog AIFM2 (86% identical), tropical clawed frog aifm2 (63% identical), zebrafish aifm2 (56% identical).
Diseases named in the same sentence as AIFM2 in open-access papers:
AIFM2 is named in the same sentence as 58 diseases in open-access papers, as found by Europe PMC text mining. Sharing a sentence is not in itself a finding about the gene and the disease. The quoted sentences say what the papers report.
lung carcinoma (10 papers, 2017 to 2025). "Further confirming the dependence of AIFM2 expression on STK11 and KEAP1 mutations, significantly higher levels of AIFM2 at both protein and mRNA levels were seen in lung cancer samples with STK11/KEAP1 mutations." (PMID 39995872, 2025). "In human lung cancer cells, toxicological stress induces the upregulation of AIFM2 and enhances apoptosis." (PMID 37371948, 2023). "Some studies have demonstrated that AIFM2 is effective for the suppression of tumorigenicity in epithelial ovarian cancer and lung cancer cells." (PMID 35111195, 2021). "The present study demonstrates that Jinfukang can induce the apoptosis of lung cancer cells by activating the expression of AIFM2." (PMID 31391058, 2019). "Previous studies of JFK demonstrated that JFK induced lung cancer cell death by regulating some apoptotic gene expression, such as AIFM2, IL-2, and Bcl2." (PMID 29234412, 2017). "Thus, NFE2L2 may inhibit ferroptosis in lung cancer cells mainly through increased AIFM2/FSP1 expression." (PMID 39025451, 2024). "Activated AIFM2 could also accelerate the apoptosis in lung cancer." (PMID 37874682, 2023). "The reason for this stems from the differences in both response to FTIs and differences in ferroptosis defense systems where STK11/KEAP1-mutant lung cancer harbors very effective anti-ferroptosis systems through SLC7A11/GPX4, AIFM2, and AKR1C." (PMID 39995872, 2025). "SLC7A11 and AIFM2 expression correlated with GPX4 inhibitors’ AUC (i.e., resistance to RSL3, ML162, and ML210) in lung cancer CLs, in agreement with the previously reported correlation in non-hematopoietic CLs in general." (PMID 39995872, 2025).
breast carcinoma (8 papers, 2021 to 2026). "Similar to circRNAs in the liver metastasis of breast cancer, these findings demonstrate that circ0060467 regulates AIFM2 and GPX4 expression by sponging miR-6805 via a ceRNA mechanism." (PMID 38244593, 2024). "CircGFRA1 has been shown to promote the progression of HER2-positive breast cancer via the miR-1228/AIFM2 axis." (PMID 37332354, 2023). "CircGFRA is abundantly expressed in HER-2 positive breast cancer, prevents apoptosis, and promotes breast cancer cell metastasis by adsorbing miR-1228 and upregulating the expression of apoptosis-inducing factor mitochondria-associated 2 (AIFM2), which is related to poor prognosis for breast cancer." (PMID 41614928, 2026). "In addition, a recent study also has suggested that AIFM2 facilitated the metastasis of HER-2-positive breast cancer cells." (PMID 37735151, 2023). "AIFM2 was overexpressed in lymphoma and under-expressed in breast cancer and CRC." (PMID 34722530, 2021). "Taken together, STAT3 and AIFM2 are two unfamiliar ferroptosis-related regulators in breast cancer, suggesting that novel ferroptosis-related signals mediated by ncRNAs may be more prevailing in breast cancer." (PMID 37065473, 2023). "The silencing of circGFRA1 can enhance ferroptosis through the circGFRA1/miR-1228/AIFM2 axis and inhibit the proliferation, infiltration, and metastasis of HER2-positive breast cancer cells." (PMID 37332354, 2023).
hepatocellular carcinoma (7 papers, 2023 to 2025). A malignant tumor that arises from hepatocytes. "In the current study, we aimed to investigate the expression pattern, clinical implication, biological functions, and molecular mechanisms of AIFM2 in hepatocellular carcinoma (HCC)." (PMID 37735151, 2023). "A study found that the release of miR-6805 from its target genes, apoptosis-inducing factor mitochondria-associated 2 (AIFM2) and GPX4, inhibited ferroptosis and promoted tumor development in hepatocellular carcinoma (HCC)." (PMID 40403492, 2025). "Here, we elucidated the clinical implications, biological functions, and molecular mechanisms of AIFM2 in hepatocellular carcinoma (HCC)." (PMID 37735151, 2023). "Subsequent experiments revealed that circ0060467 competes with AIFM2 and GPX4, thereby inhibiting cancer cell ferroptosis by binding to miR-6085 and promoting hepatocellular carcinoma progression." (PMID 38244593, 2024).
prostate carcinoma (4 papers, 2021 to 2026). A carcinoma that arises from epithelial cells of the prostate gland. "PPARA, in turn, activated the transcription of apoptosis-inducing factor mitochondria-associated 2 (AIFM2), whose upregulation inhibited ferroptosis in AnoR prostate cancer cells." (PMID 41724793, 2026). "Similarly, several studies have shown that AIFM2 represents an unfavorable prognostic factor in prostate cancer, acute myeloid leukemia and uveal melanoma." (PMID 35911966, 2022). "Additionally, the aberrant overexpression of PDHA1 in AnoR prostate cancer cells upregulates PPARA and AIFM2 expression through nuclear translocation, collectively suppressing ferroptosis and promoting metastasis." (PMID 41724793, 2026).
acute myeloid leukemia (3 papers, 2021 to 2023). Acute myeloid leukemia (AML) is a group of neoplasms arising from precursor cells committed to the myeloid cell-line differentiation. "And high expression of SLC7A11, GPX4, and AIFM2 were significantly correlated with the shortened OS of acute myeloid leukemia (LAML) patients." (PMID 34722530, 2021). "And high expression of SLC7A11, GPX4, and AIFM2 were significantly correlated with the shortened OS of acute myeloid leukemia patients." (PMID 34722530, 2021). "However, a comprehensive understanding of the roles of GPX4 and AIFM2 in acute myeloid leukemia (AML) has not yet been achieved." (PMID 38032290, 2023).
gastric cancer (3 papers, 2022 to 2025). A primary or metastatic malignant neoplasm involving the stomach. "AIFM2 was overexpressed in gastric cancer tissues; however, its roles in gastric cancer progression are unclear." (PMID 40002690, 2025). "Our results indicated that the knockdown of MIDN downregulated AIFM2 in gastric cancer." (PMID 40002690, 2025). "However, a recent study has indicated that AIFM2 act as a favorable factor for OS of gastric cancer patients, which is consistent with the findings of our study." (PMID 35911966, 2022).
bladder cancer (2 papers, 2021). "Different from SLC7A11 in bladder carcinoma, the high expression of AIFM2 was significantly associated with the good OS and RFS." (PMID 34722530, 2021).
cervical cancer (2 papers, 2011 to 2023). A primary or metastatic malignant neoplasm involving the cervix. "Apoptosis-inducing factor mitochondria associated 2 (AIFM2/FSP1) was found to be upregulated in our previous proteomics analysis whenIMPA2 gene expression was silenced in cervical cancer cells." (PMID 37140233, 2023). "Our results also suggest that paclitaxel can kill tumor cells by regulating the expression of IMPA2/AIFM2, and this mechanism provides a new target for the major role of paclitaxel as an anti-cervical cancer drug in cancer chemotherapy." (PMID 37140233, 2023). "Although evidence has shown that AIFM2 may contribute to cell apoptosis, little research has focused on its role in cervical cancer." (PMID 37140233, 2023).
colon cancer (2 papers, 2023 to 2025).
esophageal cancer (2 papers, 2021 to 2023). A primary or metastatic malignant neoplasm involving the esophagus. "In esophageal carcinoma (ESCA), GPX4 expression was significantly associated with the infiltration of macrophage and myeloid dendritic cell, and AIFM2 expression was significantly associated with the infiltration of CD4+ T cell." (PMID 34722530, 2021).
pancreatic cancer (2 papers, 2023 to 2024). "For instance, in human pancreatic cancer cells, BACH1 binds the AIFM2/FSP1 gene, though Bach1 does not bind Aifm2/Fsp1 or regulate its expression in murine cells." (PMID 39025451, 2024).
acute pancreatitis (1 paper, 2022). An acute inflammatory process that leads to necrosis of the pancreatic parenchyma.
adrenocortical carcinoma (1 paper, 2021). "High levels of SLC7A11 and AIFM2 were significantly linked with the shortened disease-free survival and overall survival (OS) in adrenocortical carcinoma (ACC), respectively." (PMID 34722530, 2021). "We found that high expression of SLC7A11, GPX4, and AIFM2 were significantly linked with the shortened disease-free survival in adrenocortical carcinoma (ACC), respectively, and high expression of SLC7A11 and AIFM2 were significantly associated with shortened OS in ACC respectively." (PMID 34722530, 2021).
esophageal adenocarcinoma (1 paper, 2021). A malignant tumor with glandular differentiation arising predominantly from Barrett mucosa in the lower third of the esophagus. "This is because esophageal adenocarcinoma-derived exosomes and microvesicles could promote the post-transcriptional downregulation of the phosphatase and tensin homolog (PTEN) and the apoptosis-inducing factor 2 (AIFM2) gene in a miR-25- and miR-210-dependent manner." (PMID 34685596, 2021).
head and neck cancer (1 paper, 2024). A primary or metastatic malignant neoplasm affecting the head and neck. "The TCGA database revealed that poorer survival of patients with higher expression of FSP1 (AIFM2) and that FSP1 is highly abnormally expressed in head and neck cancer tissues and expression increases with tumor progression." (PMID 38206305, 2024).
Insulin resistance (1 paper, 2024). Increased resistance towards insulin, that is, diminished effectiveness of insulin in reducing blood glucose levels. "AIFM2 functions as an enzyme oxidizing NADH to sustain elevated cytosolic NAD levels, facilitating vigorous glycolysis and electron transfer to the electron transport chain, thus combating diet-induced obesity and insulin resistance." (PMID 39280009, 2024).
leukemia (1 paper, 2023). A malignant (clonal) hematologic disorder, involving hematopoietic stem cells and characterized by the presence of primitive or atypical myeloid or lymphoid cells in the bone marrow and the blood. "By using the EMBL-EBI bioinformatics website, GPX4 and AIFM2 expression levels were analyzed in leukemia cell lines." (PMID 38032290, 2023). "The significant changes of GPX4 and AIFM2 expression in transcription level between different types of leukemia and normal control." (PMID 38032290, 2023).
liver cancer (1 paper, 2022). An epithelial or non-epithelial malignant neoplasm that arises from the liver. "Several studies have shown that AIFM2 translocation could promote the apoptosis of breast, gastric, and liver cancer cells in a caspase-independent manner." (PMID 36313179, 2022).
lymphoblastic lymphoma (1 paper, 2019). A lymphoma composed of immature small to medium-sized precursor lymphoid cells (lymphoblasts). "MEG3 can regulate the miR-214/AIFM2 axis to inhibit the growth of lymphoblastic lymphoma." (PMID 31531526, 2019).
steatosis (1 paper, 2023). Increased lipid within the cytoplasm of cells. "Immunohistochemistry demonstrated that the protein expression of AIFM2 was markedly increased in liver tissue from NASH patients compared to that in liver tissue from simple steatosis patients." (PMID 37629045, 2023).
urachal carcinoma (1 paper, 2018). "This suggests a regulatory role of RSU1 and AIFM2 in urachal carcinoma metastases." (PMID 29901861, 2018).
viral infection (1 paper, 2022). "The Aifm2 gene encodes a flavoprotein oxidoreductase that binds single-stranded DNA and can cause apoptosis due to viral infection." (PMID 36014997, 2022).